SIX1 (SIX homeobox 1)
Diseases named in the same sentence as SIX1 in open-access papers (continued):
Sharing a sentence is not in itself a finding about the gene and the disease.
non-small cell lung carcinoma (6 papers, 2021 to 2024). A group of at least three distinct histological types of lung cancer, including non-small cell squamous cell carcinoma, adenocarcinoma, and large cell carcinoma. "The homeoprotein SIX1 is upregulated in non-small cell lung cancer (NSCLC) and associated with NSCLC tumorigenesis and progression." (PMID 33686961, 2021). "In a previous study, tanshinone IIA inhibited glycolysis in non-small-cell lung cancer cells by modulating the transcription factor SIX1." (PMID 38792080, 2024). "Overexpression of miR-186-5p inhibited cellular proliferation, migration, and invasion in non-small-cell lung cancer cells and promoted sensitivity to paclitaxel by binding to sine oculis homeobox 1 (SIX1)." (PMID 37841425, 2023). "However, the prognostic value and biological function of SIX1 in non-small cell lung cancer (NSCLC) remain unclear." (PMID 35069900, 2022).
thyroid cancer (6 papers, 2019 to 2024). "SIX1 has been shown to be upregulated in thyroid cancers and associated with tumor size and metastasis." (PMID 38886487, 2024). "Since PTC is the most common type of thyroid carcinoma and also occupied the majority of the tissue microarrays in this study, we next examined the association of SIX1 and EYA1 expression with clinicopathological parameters." (PMID 31921695, 2019). "Mutations in EYA1 may cause dysregulation and act as a tumor promoter with SIX1 via activation of STAT3 signaling in thyroid carcinomas." (PMID 38067373, 2023). "SIX1, a tumor promoter, promoted the proliferation and invasion of thyroid carcinoma via activation of STAT3 signaling and its downstream targets in an EYA1‐dependent manner." (PMID 32851683, 2020). "Since SIX1 is a DNA-specific transcriptional factor, whereas EYA1 basically acts as a co-factor to increase SIX1-dependent function, we mainly focused on the functional role of SIX1 in thyroid cancer for first." (PMID 31921695, 2019). "Taken together, these data demonstrate that SIX1 promoted cell cycle progression in thyroid cancer cells." (PMID 31921695, 2019). "In the present study, our results first showed that SIX1 protein elevated in thyroid malignant tumor." (PMID 31921695, 2019). "In this study, thyroid carcinoma tissue microarray staining was employed to identify the expression patterns of SIX1 and its co-activator EYA1." (PMID 31921695, 2019). "Compared with the control tissues, a marked upregulation in SIX1 expression levels was observed in the liver, colon, breast, ovary, kidney, lung, and prostate tumor tissues, while a slight downregulation was observed in thyroid cancer tissues." (PMID 37427884, 2023). "Besides, SIX1 promoted the proliferation and invasion of thyroid carcinoma via activation of STAT3 signaling and its downstream targets in an EYA1-dependent manner." (PMID 31921695, 2019). "Importantly, SIX1 strongly correlated with EYA1 in thyroid carcinoma tissue microarray." (PMID 31921695, 2019). "Based on these data, high expressions of SIX1 and EYA1 are closely correlated with thyroid malignant tumor." (PMID 31921695, 2019). "Similarly, higher Spearman’s risk and reduced survival were observed for LGG, STAD, mesothelioma (MESO), pheochromocytoma and paraganglioma (PCPG), and thyroid carcinoma (THCA) patients expressing SIX1, collectively suggesting the prognostic value of SIX1 in these cancers." (PMID 35201514, 2021). "However, the functional relationship of SIX1 and EYA1 in thyroid cancer remains to be discovered." (PMID 31921695, 2019).
lymph node metastasis (5 papers, 2019 to 2024). "This study we found that SIX‐1 expression was frequently up‐regulated in BC patients, and high level of SIX‐1 was associated with lymph node metastasis and correlated with unfavourable OS, RFS and DMFS." (PMID 32227618, 2020). "Importantly, up‐regulation of SIX‐1 showed strong association with lymph node metastasis and AJCC stage in BC patients." (PMID 32227618, 2020). "In papillary thyroid carcinoma, high expressions of SIX1 and EYA1 were associated with advanced age, lymph node metastasis and clinical stage." (PMID 31921695, 2019). "High SIX1 status positively correlated with advanced TNM stage and the presence of lymph node metastasis." (PMID 32201523, 2020). "Higher levels of SIX1 and EYA1 were found correlated with advanced age and lymph node metastasis, which are well-known poor prognostic factors in PTC." (PMID 31921695, 2019).
pulmonary fibrosis (5 papers, 2019 to 2024). Chronic progressive interstitial lung disorder characterized by the replacement of the lung tissue by connective tissue, leading to progressive dyspnea, respiratory failure, or right heart failure. "SIX1-driven expression of macrophage migration inhibitory factor (MIF) was attributed to the process of lung fibrosis." (PMID 36750914, 2023). "Taken together, these results demonstrate that prophylactic deletion of Six1 prior to BLM exposure protects mice from the development of lung fibrosis observed both histologically and physiologically." (PMID 35420997, 2022). "Conditional deletion of Six1 in AT2 cells prevented or halted BLM-induced lung fibrosis, as measured by a significant reduction in histological burden of fibrosis, reduced fibrotic mediator expression, and improved lung function." (PMID 35420997, 2022). "We have demonstrated that deletion of Six1 prophylactically or therapeutically prevents or halts the development of lung fibrosis." (PMID 35420997, 2022). "Our findings support a strong basis for the continued work on SIX1 in the alveolar epithelium and have the potential to lead to many insights into the molecular mechanisms of pulmonary fibrosis." (PMID 35420997, 2022). "Taken together, these results demonstrate that deletion of Six1 during active injury attenuates the progression of ongoing lung fibrosis." (PMID 35420997, 2022). "To identify how Six1 expression promotes lung fibrosis, we overexpressed Six1 in MLE12 cells and performed RNA-Seq to identify candidate genes." (PMID 35420997, 2022). "In addition, studies have also found that miR-448-5p overexpression inhibited TGF-β1-induced EMT and pulmonary fibrosis in asthmatic mice by targeting SIX1 expression." (PMID 36750914, 2023). "AT2-specific SIX1 overexpression in vivo exacerbates lung fibrosis." (PMID 35420997, 2022). "We tested our hypothesis that SIX1 is a molecular driver of lung fibrosis that can be targeted therapeutically." (PMID 35420997, 2022). "SIX1 is upregulated in 2 distinct mouse models of pulmonary fibrosis." (PMID 35420997, 2022). "Deletion of Six1 from AT2 cells protects mice from BLM-induced lung fibrosis." (PMID 35420997, 2022). "The latest research showed that E2F1 affected TGF-β1-induced pulmonary fibrosis and epithelial-mesenchymal transition (EMT) in BEAS-2B cells through the miR-106b-5p/E2F1/SIX1 signaling pathway." (PMID 37128280, 2023). "Six1 was also upregulated in bleomycin-treated (BLM-treated) mice and in a model of spontaneous lung fibrosis driven by deletion of Telomeric Repeat Binding Factor 1 (Trf1) in AT2 cells." (PMID 35420997, 2022). "The role of the developmental transcription factor Sine oculis homeobox homolog 1 (SIX1) in the pathophysiology of lung fibrosis is not known." (PMID 35420997, 2022). "Thus, we hypothesize that SIX1 expression is elevated in IPF and that it is a molecular driver of lung fibrosis that can be targeted therapeutically." (PMID 35420997, 2022).
renal agenesis (5 papers, 2011 to 2022). Renal agenesis (RA) is a form of renal tract malformation characterized by the complete absence of development of one or both kidneys (unilateral RA or bilateral RA respectively), accompanied by absent ureter(s). "We previously reported that renal agenesis associated with Six1-deficiency can be rescued in Eya1Six1/+;Six1−/− mice." (PMID 35178390, 2022). "Consistent with these differential expression patterns, germline Six2 deletion in mice leads to renal hypoplasia due to depletion of the nephron progenitors, while Six1 knockout causes renal agenesis due to malformation of the MM." (PMID 35178390, 2022). "Mutations in EYA1, PAX2, SIX1, or SIX2, have been found in a subset of human patients with renal agenesis or hypoplasia." (PMID 27442016, 2016). "For instance, Six1 knockout mice display renal agenesis despite apparently normal levels of GDNF mRNA." (PMID 24143282, 2013). "The Eya1, Pax2, and Six1 transcription factors are each required for activation and/or maintenance of Gdnf expression in the metanephric mesenchyme and mice lacking any one of them die perinatally with bilateral renal agenesis." (PMID 27442016, 2016).
sarcoma (5 papers, 2015 to 2023). A usually aggressive malignant neoplasm of the soft tissue or bone. "Our mechanistic data were further strengthened by analyses of sarcoma patient datasets, in which most collagen members were upregulated in cancerous tissue compared with normal tissue and were positively correlated with the expression levels of Six1." (PMID 34782761, 2021). "Our results as well as those of others implicate Six1 in sarcoma growth however its functional links to CTAG1B/A or to RANBP2 remain to be established and underscore the complexity of sarcoma biology." (PMID 35664317, 2022). "Notably, SIX1 targeted the promoters of the amino-terminal enhancer of split (AES) and fused in sarcoma (FUS), which are cofactors of nuclear factor-κB (NF-κB) subunit RELA, and then inhibited the transactivation function of RELA." (PMID 34513929, 2021).
acute myelocytic leukemia (4 papers, 2020 to 2023). "On the contrary, SETDB1 inhibits the expression of genes associated with acute myeloid leukemia (AML), such as Dock1, Hoxa9, and Six1, to delay MLL-AF9-mediated disease progression by promoting the differentiation of leukemia cells." (PMID 38057834, 2023). "SIX1 is a target gene controlled by WNT in acute myelocytic leukemia." (PMID 32258386, 2020). "Besides, a previous report indicated that the SIX1 can be transcriptional regulated by a transducer of WNT/β-catenin signaling, TCF7L2 in acute myelocytic leukemia, and WNT/β-catenin signaling promotes skeletal muscle development by increasing SIX1 levels (Petropoulos, Skerjanc 2002)." (PMID 32399910, 2021).
Branchio-otic syndrome (4 papers, 2021 to 2023). "Pathogenic heterozygous SIX1 variants (predominantly missense) occur in branchio-otic syndrome (BOS), but an association with craniosynostosis has not been reported." (PMID 33436522, 2022).
breast tumor (4 papers, 2010 to 2025). "Finally, we show for the first time that Six1 correlates with p-ERK in human breast tumors, suggesting that this mechanism is relevant to the human disease." (PMID 22765220, 2012).
cardiac hypertrophy (4 papers, 2016 to 2024). "Previous studies had revealed that Six1 and its cofactor Eya2 could simulate heart hypertrophy through directly up-regulating mTOR." (PMID 27007909, 2016). "Further, FBXW7 has been reported as a regulator of cardiac hypertrophy, likely through controlling the protein stability of EZH2 (enhancer of zeste homology 2) and the transcription of SIX1 (sine oculis homeobox homolog 1)." (PMID 35327608, 2022).
osteosarcoma (4 papers, 2020 to 2023). A usually aggressive malignant bone-forming mesenchymal neoplasm, predominantly affecting adolescents and young adults. "In osteosarcoma cells, overexpression of SIX1 led to decreased caspase-3 and caspase-7 with reduced apoptosis." (PMID 34490256, 2021). "SIX1 promotes cell proliferation and tumorigenesis in osteosarcoma via regulating phosphatase and tensin homolog (PTEN)/ phosphoinositide-3-kinase (PI3K)/AKT signaling cascade." (PMID 32258386, 2020).
papillary thyroid carcinoma (4 papers, 2019 to 2023). "In papillary thyroid cancer tissues, protein expressions of SIX1 and EYA1 are positively correlated, SIX1 stabilizes EYA1 at the post-transcriptional level and activates STAT3 signaling requiring EYA1." (PMID 36750914, 2023). "The knockdown of SIX1 suppressed the process of EMT in papillary thyroid carcinoma through inhibiting the TGF-β/SMAD2/3 signaling pathway." (PMID 36750914, 2023). "Association between SIX1/EYA1 expression and clinicopathologic factors in papillary carcinoma (TH8010 + TH802a)." (PMID 31921695, 2019). "A similar mechanism is found for SIX1 in papillary thyroid carcinoma." (PMID 35095892, 2021). "Papillary thyroid cancer cell lines, BCPAP, and TPC-1 cells were used to investigate the potential mechanism of SIX1 in vitro and in vivo." (PMID 31921695, 2019). "Although some studies in other cancers indicated that SIX1 regulates EMT processes through the TGF-β/Smad2/3 signaling pathway in papillary thyroid cancer, there is no direct evidence that SIX1 induces EMT via the TGF-β/Smad2/3 signaling pathway in GC." (PMID 35458126, 2022). "Our study indicated that SIX1 and EYA1 might be used as malignancy hallmarks in papillary thyroid cancer." (PMID 31921695, 2019).
cardiomyopathy (3 papers, 2015 to 2018). A disease of the heart muscle or myocardium proper. "Interestingly, Six1 has been recently found to be deregulated in cardiomyopathy induced by Nkx2-5 point mutation or in human patients." (PMID 29979676, 2018). "Accordingly, we identified differential expression in several genes in Idh2R140Q mouse hearts that, when dysregulated, could be implicated in cardiomyopathy, including downregulation of Hopx and Tmod4 and upregulation of Six1 and Nmrk2." (PMID 27469509, 2016). "This shows that interruption of the EYA4 interaction with SIX1 and SIX2 impairs cardiac function, resulting in cardiomyopathy." (PMID 25781927, 2015).
colon cancer (3 papers, 2012 to 2023).
esophageal cancer (3 papers, 2019 to 2023). A primary or metastatic malignant neoplasm involving the esophagus. "According to a previous publication, an esophageal cancer cell line Eca-109 have high endogenous SIX1 expression." (PMID 32201523, 2020).
leukemia (3 papers, 2015 to 2025). A malignant (clonal) hematologic disorder, involving hematopoietic stem cells and characterized by the presence of primitive or atypical myeloid or lymphoid cells in the bone marrow and the blood. "Increased Suv39h1 expression led to the inactivation of Hoxb13 and Six1, as well as reversion of Hoxa9/Meis1 downstream target genes, which in turn decelerated leukemia progression." (PMID 33037410, 2020). "Herein, we demonstrate that Suv39h1 is significantly down-regulated in AMLs and could function as a tumor suppressor in MLL-rearrangement induced leukemia by regulating Hoxb13 and Six1, as well as Hoxa/Meis1 downstream signature genes." (PMID 33037410, 2020). "Of note, SIX1 and EYA1 are targets of the onco-fusiongene MLL-ENL in leukemia, highlighting their role in hematopoietic malignancies." (PMID 26473286, 2015).
branchiootic syndrome (2 papers, 2021 to 2022). "SIX1 is a master regulator in multiple tissues and ONECUT1 is a transcription factor of the liver; and are associated with the craniofacial disorders branchiootic syndrome and amelogenesis imperfecta, respectively." (PMID 35711735, 2022).
CHARGE syndrome (2 papers, 2020 to 2022). CHARGE syndrome is a multiple congenital anomaly syndrome characterized by the variable combination of multiple anomalies, mainly Coloboma; Choanal atresia/stenosis; Cranial nerve dysfunction; Characteristic ear anomalies (known as the major 4 C's). "Several neural crest regulatory molecules are known to cause ear/kidney syndromes with variable expression of both ear and kidney phenotypes (e.g., EYA1, SIX1, SIX5, CHD7, MASP1, TBX1), involved in BOR/BO syndrome, CHARGE syndrome, 3MC syndrome and DiGeorge syndrome." (PMID 32585897, 2020).
chronic kidney disease (2 papers, 2018 to 2025). Impairment of the renal function secondary to chronic kidney damage persisting for three or more months. "Such regulation also matters in mammals, e.g., for the MSL2 targets Six1-4 or Sall1, whose haploinsufficiency causes syndromes associated with hearing loss, chronic renal failure, limb, and ear anomalies in humans." (PMID 30194291, 2018). "Among the putative human Six1 targets are also the metallophosphoesterase MPPED2, which has been associated with chronic kidney disease, and the serine/threonine kinase 39 (STK39), also called SPAK." (PMID 40213817, 2025).
Ewing sarcoma (2 papers, 2023 to 2024). A small round cell tumor that lacks morphologic, immunohistochemical, and electron microscopic evidence of neuroectodermal differentiation. "Along with myogenic differentiation regulators, DiPRO1 can control neuronal development in RMS and Ewing sarcoma through SIX1 targets (Fig. EV3D,C)." (PMID 39009887, 2024).
fibrosarcoma (2 papers, 2019 to 2021). A malignant mesenchymal fibroblastic neoplasm affecting the soft tissue and bone. "Collectively, these results indicate enhanced cellular plasticity in SIX1-expressing fibrosarcomas, as shown by the activation of Sox2 and additional markers of stemness or alternative cell linages, and the concomitant loss of mesenchymal markers." (PMID 30723235, 2019).
glioblastoma (2 papers, 2020 to 2022). The most malignant astrocytic tumor (WHO grade IV). "We also explored the function of miR‐155‐3p in the regulation of cell cycle, proliferation, apoptosis and resistance to TMZ by targeting Six1 in glioblastoma cells with wild‐type Six1." (PMID 32220051, 2020). "SIX1 could promote proliferation via upregulating the connective tissue growth factor (CTGF) in glioblastoma cells." (PMID 35069900, 2022).
Hodgkins lymphoma (2 papers, 2015 to 2021). A heterogeneous group of malignant lymphoid neoplasms of B-cell origin characterized histologically by the presence of Hodgkin and Reed-Sternberg (HRS) cells in the vast majority of cases. "GATA2 is suppressed by SIX1 and SIX2 during erythropoiesis but activated by SIX1 in Hodgkin lymphoma." (PMID 34768865, 2021).
keloid (2 papers, 2017 to 2022). An irregularly shaped, elevated mark on the skin caused by deposits of excessive amounts of collagen during wound healing. "In terms of expression level, BMP4, MSX1, TBX2, SIX1, DLX5, and DLX2 were lowly expressed, while HAND2, IRX1, EDN1, and MEF2C were highly expressed in keloid fibroblasts." (PMID 35047146, 2022).
kidney damage (2 papers, 2021 to 2024). "The overexpression of SIX1 in mouse kidney resulted in the promotion of cell proliferation and migration and reduced the infiltration of Mophs thus attenuating kidney damage." (PMID 34513929, 2021). "Our study provides evidence that SIX1 involved in cell proliferation, migration, and anti-inflammation in the I/R model, which might be a potential therapeutic target that could be used to ameliorate kidney damage." (PMID 34513929, 2021). "However, whether SIX1 was reactivated after I/R injury and affected cell proliferation, migration, as well as NF-κB activities thus reduced kidney damage has not been reported." (PMID 34513929, 2021).
Obesity (2 papers, 2020 to 2024). Accumulation of substantial excess body fat. "However, liver‐specific SIX1 deficiency repressed HFD‐induced obesity and body weight gain, NAFLD, and hepatic TG and TC levels." (PMID 39258807, 2024).